WEE1 (WEE1 G2 checkpoint kinase)
Diseases named in the same sentence as WEE1 in open-access papers (continued):
Sharing a sentence is not in itself a finding about the gene and the disease.
tumor (continued). "Unlike Chk1 inhibition, there is currently limited evidence for the use of Wee1 inhibitors in radiosensitising HNSCC tumour models." (PMID 39994186, 2025). "Future studies should focus on optimizing DHCR7-targeted inhibitors and rationally combining them with cell cycle checkpoint modulators, such as WEE1 inhibitors, or ER stress-enhancing agents to amplify tumor cell killing while minimizing toxicity." (PMID 41249736, 2025). "Preclinical studies have demonstrated that WEE1 inhibition enhances the cytotoxic effects of several chemotherapies, leading to increased tumor regression and reduced therapy resistance." (PMID 40565165, 2025). "Next, we performed immunostaining using the transplanted tumor specimens to evaluate the effect of the WEE1 inhibitor on the tumor immune microenvironment." (PMID 39335109, 2024). "In the clinical setting, many clinical trials investigating the efficacy of Wee1 inhibition in various contexts have been conducted, with several demonstrating anti-tumor activity." (PMID 38730598, 2024). "Whilst the potential for Chk1 and Wee1 inhibitors to act as tumour radiosensitisers is compelling, there remain some uncertainties, and the mechanisms ultimately leading to cell death in the defined tumour cell models needs to be further investigated." (PMID 39272874, 2024). "Inhibiting the Wee1 kinase as an approach for radiosensitising tumour cells was proposed following the development of the first Wee1 inhibitor PD0166285." (PMID 39272874, 2024). "PARG-depleted cells demonstrate an overreliance on the ATR/CHK1/WEE1 damage response pathway, highlighting a potential therapeutic target for such tumours." (PMID 39135999, 2024). "Additional preclinical work demonstrated that the Wee1 inhibitor AZD1775, alone and in combination with irinotecan or vincristine, led to G2/M phase arrest, increased DNA damage, and had anti-tumor activity against in vivo models of high-risk RMS." (PMID 38730598, 2024). "RNA sequencing and immunohistochemistry analyses of mouse tumors revealed that treatment with the WEE1 inhibitor activated tumor immunity and suppressed stromal reactions." (PMID 39335109, 2024). "In vivo evaluations were executed to ascertain the inhibitory effect of WEE1 inhibitors on tumor growth in mice." (PMID 38169513, 2024). "In treatment experiments using the orthotopic transplanted mouse model of CRC, the WEE1 inhibitor significantly reduced tumor volume, and immunostaining revealed the infiltration of CD8-positive T cells into the tumors in the treated group." (PMID 39335109, 2024). "Of note, the anti-tumor activity of Wee1 inhibition can be counteracted by tumor overexpression of Myt1, a kinase that also regulates the G2/M checkpoint and has somewhat overlapping activity with Wee1." (PMID 38730598, 2024). "Survival of cells and tumor growth in-vitro and in-vivo caused by the combination of the CHK1 inhibitor SRA737 and the WEE1 inhibitor adavosertib was studied in OVCAR3 and MDA-MB 436 cells." (PMID 39516567, 2024). "Collectively, pre-clinical evidence for targeting Wee1 in combination with radiation suggests this as a promising therapeutic avenue in a number of different tumour types." (PMID 39272874, 2024). "Nevertheless, PD0166285 initially demonstrated that Wee1 was a promising new target for increasing radiosensitisation in a variety of different tumour cell types." (PMID 39272874, 2024). "A follow-up study in NB xenografts demonstrated that the Wee1 inhibitor adavosertib was minimally efficacious as a single agent but exhibited anti-tumor activity when combined with irinotecan." (PMID 38730598, 2024).
tumor (continued). "Currently, the small‐molecular WEE1 inhibitor (ZN‐c3) has demonstrated good safety in early‐phase clinical trials, with 17% of participants with various tumours exhibiting PR to this inhibitor." (PMID 39073010, 2024). "In this study, we wanted to evaluate changes in the tumor immune microenvironment induced by WEE1 inhibition, so it was necessary to use a model of allogeneic immune response." (PMID 39335109, 2024). "This article aims to comprehensively review the existing knowledge on the implication of WEE1 as a therapeutic target in tumor progression and drug resistance." (PMID 38231277, 2024). "Though Wee1 inhibitors have shown promising anti-tumor effects in vitro and in vivo, few studies explore their clinical efficacy in HNC." (PMID 38612819, 2024). "Previous studies have revealed that Wee1 inhibitor had great anti-tumor potential together with other G2/M arresting or DNA damaging therapeutic compounds in DLBCL." (PMID 38589831, 2024). "In the orthotopic mouse model of CRC, tumor volume was significantly reduced in the WEE1 inhibitor-treated group compared to that in the control group." (PMID 39335109, 2024). "In our study, targeting SHCBP1 showed a consistent strong inhibitory effect on tumour progression both in vitro and in vivo, likely mainly through WEE1 kinase downregulation." (PMID 38365687, 2024). "MK-1775 was the first Wee1 inhibitor that progressed to clinical trials, showing a plethora of preclinical evidence for single agent and combinatorial therapy enhancements in tumour treatments." (PMID 39272874, 2024). "For tumours with moderate levels of baseline TILs, PD-1 checkpoint blockade confers additional anti-tumour activity in combination with the olaparib and WEE1 inhibition, even at reduced doses, to achieve more durable anti-tumour efficacy." (PMID 37582853, 2023). "We found EphA2- and Wee1-targeted therapies had synergistic effects in vitro, and the combination therapy led to enhanced anti-tumor efficacy in vivo." (PMID 36835335, 2023). "PD-1 inhibitors have been found to enhance WEE1 inhibition and promote cytotoxic T-cell-mediated clearance of tumour cells, thereby reducing accumulation of tumour infiltrating neutrophils." (PMID 38057851, 2023). "Of note, synergy between CHK1/2 inhibition and WEE1 inhibition is common across models from diverse tumor types." (PMID 37380628, 2023). "Nonetheless, AZD1775 at 30 mg/kg in both monotherapy and combined treatment groups resulted in a decrease in phosphorylation of CDC2 (CDK1) at Tyr15 indicating effective inhibition of WEE1 in the AT3 tumours at this reduced dose." (PMID 37582853, 2023). "At the same time, deleting the WEE1 protein increases the sensitivity of tumor cells to treatment and produces a synthetic lethal effect." (PMID 37305685, 2023). "It is well established that Wee1 is an important cell cycle regulatory signal in tumor cells, and its role in regulating DDR and genomic stability is widely acceptable." (PMID 37102239, 2023). "At both the protein and mRNA levels, WEE1 exhibited significantly higher expression in tumor samples." (PMID 37781709, 2023).
tumor (continued). "In this study, we show that WEE1 inhibition can sensitise BRCA1/2 wild-type TNBC to PARP inhibitors resulting in synergistic anti-tumour efficacy with increased DNA damage, apoptosis, replication stress, and STING pathway activation." (PMID 37582853, 2023). "Recent studies have focused on the link between Wee1 inhibitors and tumor immunity to find new choices for combinational therapy strategies." (PMID 37109350, 2023). "In preclinical studies, the classical components of cell-cycle progression and DNA-damage repair, such as ATM, DNA-PKcs, ATR, CHK1, CHK2 and WEE1, have shown to be very promising targets for radiosensitizing tumor cells by applying small-molecule inhibitors." (PMID 36313934, 2023). "Consistently, increased levels of WEE1 have been shown to correlate with tumor progression and poor progression-free survival." (PMID 36509894, 2023). "Applying WEE1 inhibitors to tumor cells revealed a significant reduction in the expression of M2 macrophages and Treg immunosuppressive cells in TME, reversing the suppressive TME and increasing the sensitivity of tumor cells to immunotherapy." (PMID 37305685, 2023). "Combined PARP and WEE1 inhibitor treatment at clinically relevant doses reduced the growth rates of both tumour models as well as significantly improved survival compared with olaparib monotherapy and the vehicle treated controls." (PMID 37582853, 2023). "We demonstrate that combined PARP and WEE1 inhibition are synergistic in controlling tumour growth in BRCA1/2 wild-type TNBC preclinical models." (PMID 37582853, 2023). "Inhibition of WEE1 protein expression disrupts cell cycle regulation, increases DNA damage and genomic instability, and affects tumor cell development." (PMID 37305685, 2023). "As such, the combination of WEE1 inhibitors (WEE1i) with PARPi has the potential to increase anti-tumour activity over and above that of PARPi treatment alone by exacerbating PARPi-induced replication stress." (PMID 37582853, 2023). "Our analysis utilizing Western blotting (WB), immunohistochemistry (IHC), and immunofluorescence staining revealed a substantial elevation of WEE1 levels within the tumor tissues, in comparison to the corresponding adjacent tumor tissues." (PMID 37662954, 2023). "A strategy of releasing tumor cells from a cell cycle block into a phase where the cells are sensitive to Wee1 inhibition was used in a preclinical study with sarcoma." (PMID 35251998, 2022). "Here, we report the tumor-intrinsic and previously unexplored roles of WEE1 pathway targeting in regulating the antitumor immune response in multiple SCLC models." (PMID 35584676, 2022). "WEE1 inhibitor increases tumor-specific cytotoxicity and shows a positive effect on immune response after radiation by dendritic cell activation, which can be combined with immune therapy." (PMID 35875060, 2022). "Inhibiting Wee1 kinase not only boosts chemotherapeutic drug sensitivity but also forces tumor cells into mitosis, even if the DNA is damaged." (PMID 36575478, 2022). "The tumor suppressor, WEE1 regulates the replication forks and genome stability, inhibiting the replication of cells with altered DNA in humans." (PMID 36456907, 2022). "A recent study on non-brain murine tumors showed that, in addition to sensitization of radiation-induced tumor cell inactivation, inhibition of the WEE1 kinase also enhanced the response to immune checkpoint blockade." (PMID 35158967, 2022). "On the other hand, an enhanced response to the WEE1 inhibitor MK-1775 in combination with RT was observed after knockdown or knockout of p21 in tumor and normal cell lines." (PMID 35158967, 2022). "Most notably, the current study provides mechanistic insight into both tumor-intrinsic and immunologic effects of WEE1 targeting in SCLC." (PMID 35584676, 2022).
tumor (continued). "We identified elevated levels of the WEE1 gene in all tumour lines when compared to human RNA from healthy brain tissues." (PMID 36142793, 2022). "In the current study, we found that WEE1 inhibition increased tumor-infiltrating T cells by activating the innate antitumor immune-response pathway in SCLC models." (PMID 35584676, 2022). "The combination of WEE1 inhibition with AZD1775 and anti-PD-L1 antibody caused significant tumor regression, with tumor volumes remaining below baseline for approximately 70% of animals." (PMID 35584676, 2022). "In this regard, inhibitors of the ATR axis, including ATR, CHK1, and WEE1, have been used to effectively target tumor cells with increased replication stress." (PMID 35418189, 2022). "Our study found the up-regulated WEE1 in CC and further proved that silenced WEE1 rescued the pro-tumor effect of inhibited miR-625-5p on CC." (PMID 35477702, 2022). "This contrasted with prior murine model results where low concentrations of Wee1 inhibitor were observed in both brain and tumor tissue, using orthotopic GBM xenografts." (PMID 35603818, 2022). "As a result, the rapidly dividing SCLC tumor cells are under substantial replication stress and are heavily reliant on G2/M cell-cycle checkpoint proteins, like WEE1, to maintain survival." (PMID 35584676, 2022). "WEE1, an important regulator of G2/M phase of the cell cycle, has been recently shown to play an important role in dictating anti-tumor immune responses in preclinical small cell lung cancer models." (PMID 36551637, 2022). "We also compared expression levels of paired normal and tumor samples in the TCGA dataset, and found down-regulated levels of WEE1 and WEE2 and up-regulated levels of PKMYT1 in tumors." (PMID 34959223, 2021). "Among all treatments tested in the MGT4 cell line (single or combined drugs), we uncovered that the simultaneous inhibition of BCL‐XL and WEE1 drastically reduced tumor cell viability." (PMID 33552868, 2021). "MiR-194 acts as a tumor suppressor in LSCC by inhibiting Wee1 expression, and miR-340-3p has been demonstrated to play critical roles in LSCC progression." (PMID 34455918, 2021). "Orthotopic studies showed that combinatorial BCL‐XL+WEE1 inhibition reduced in vivo tumor growth of MGT11Luc cells injected into the mammary fat pad of mice." (PMID 33552868, 2021). "The WEE1 mRNA levels were increased in tumor tissues and the positive staining of WEE1 was found in the most of 102 CRC tissue samples." (PMID 34201502, 2021). "SCLC patients with higher Wee1 tumor expression had a better prognosis compared with the patients with lower expression in a large cohort of resected SCLC patients in our study." (PMID 33320980, 2021). "Few studies have evaluated the role of microRNAs (miRNAs), long non-coding RNAs (lncRNAs) and small-interference RNAs (siRNAs) that are able to modulate Wee1 expression in tumor cells and their involvement in tumor progression." (PMID 34639030, 2021). "This study was conducted to investigate the anti-tumor effects of the WEE1 inhibitor, AZD1775, and the mechanism responsible for its potentiation of sensitivity to olaparib (a PARP inhibitor) via the modulation of DDR in TNBC cells." (PMID 32555285, 2020). "Wee1-like kinase (WEE1) was amongst the most promising targets for both tumor and precancerous cells." (PMID 32047167, 2020).
tumor (continued). "While previous studies have shown MEK, CDK4/6 and WEE1 as promising kinase targets for inhibiting tumor growth, druggable kinases against RMS self-renewal have been poorly characterized." (PMID 32363002, 2020). "All tumor cell lines showed a decreased cell viability with a value ≤ −0.5 upon WEE1 knockdown, except VU-SCC-1604." (PMID 32047167, 2020). "Conversely, ATR’s functions in regulating G2-M checkpoint activation, replication fork stability and late-origin firing appear to dominate ATR-inhibitor efficacy, with ATR and WEE1 inhibitors showing efficacy in tumours with high replication stress." (PMID 32444694, 2020). "In conclusion, the up-regulation of BUB1B, CCNA2, CDC20, CDK1, and WEE1 in tumor tissues are associated with worse OS and DFS in PDAC and is correlated with advanced tumor stage and tumor development." (PMID 30765611, 2019). "The combined inhibition of Wee1 and Chk stopped tumor growth in resistant and even more so in sensitive tumors, supporting the clinical relevance of our findings." (PMID 30728057, 2019). "The expression of PLK1 and CHEK1 was significantly higher in tumor tissues than in normal tissues, whereas WEE1 expression was significantly lower in tumor tissues than that in normal tissues." (PMID 31387297, 2019). "Using qPCR on tissue RNA, we demonstrated the significant downregulation of FXBO31 and WEE1 in the tumor tissue compared to healthy adjacent mucosal tissue." (PMID 31616639, 2019). "The WEE1 inhibitor MK1775 alone at a clinically relevant dosage (60 mg kg−1) already showed its inhibitory effect on Tsc2-null tumor growth in vivo." (PMID 30266942, 2018). "Together, the WEE1 inhibitor can be used for TSC2-null tumor treatment by accelerating release from the G2/M DNA damage checkpoint dampened by hyperactivation of mTORC1." (PMID 30266942, 2018). "A) Box plots showing the level of expression of Wee1 mRNA in different tumor samples, extracted from CCLE." (PMID 30068368, 2018). "We have previously shown that treatment of brachyury-high tumor cells with the WEE1 inhibitor, MK-1775, is able to overcome tumor resistance to immune-mediated killing by decreasing WEE1 activity and increasing the level of functional CDK1." (PMID 29774202, 2018). "Using a newly characterized and culturable murine NK cell line, we demonstrated that WEE1 kinase inhibition can be used to prevent G2/M cell cycle checkpoint activation and sensitize tumor cells to granzyme B-dependent NK lysis." (PMID 29925431, 2018). "One potential therapeutic avenue for improving the lysis of brachyury-high tumor cells consists of tumor pretreatment with an inhibitor of the G2 checkpoint kinase, WEE1, which normally suppresses the activity of CDK1 via phosphorylation on Tyr-15." (PMID 29774202, 2018). "Wee1-inhibiting MK1775 was shown to have multiple effects on tumour cells: First, replicative stress based on inactivated CDC2, enhanced initiation of DNA-replication and thus, shortage of nucleotides and lowered replication fork speed was observed." (PMID 30253737, 2018). "Due to the central role in the DNA damage response, different cell cycle checkpoint inhibitors (ATM/ATR/CHK1/CHK2/WEE1 inhibitors) have been developed to specifically inhibit the mechanisms by which tumor cells respond to DNA damaging agents." (PMID 28356161, 2017). "Inhibition of Wee1 has been expected to abrogate the G2/M checkpoint, forcing tumor cells with DNA damage to enter into unscheduled mitosis to undergo cell death." (PMID 28978051, 2017). "The immunohistochemical staining indicated a significant decrease in Wee1 expression in tumours treated with in vivo‐ready mirVanaTM miR‐15b mimics and in tumours established with KHOSMR cells previously transfected with miR‐15b precursor." (PMID 28145098, 2017). "Many WEE1 inhibitors have been developed to override cell cycle checkpoint signaling and, consequently, to improve the sensitivity of tumor cells to the toxic effect of different genotoxic agents." (PMID 28356161, 2017).